PARP1 (poly(ADP-ribose) polymerase 1)
Diseases named in the same sentence as PARP1 in open-access papers (continued):
Sharing a sentence is not in itself a finding about the gene and the disease.
tumor (continued). "For example, we showed that whereas both PARP1 and PARP2 co-express with cell cycle genes in tumor samples consistent with their known roles in DNA repair, only PARP2 strongly co-expresses with many C2H2-type zinc finger genes in normal tissues." (PMID 29259170, 2017). "When ERβ is activated by the selective agonist KB9520, SIRT1 and FOXM1 are down regulated, resulting in increased acetylated AKT1 and interaction with PARP1, HSC70 and GADPH in tumor cells, both in vitro and in vivo." (PMID 26885609, 2016). "We also treated primary WM tumor cells with VLX1570 and noted apoptosis and PARP-1 cleavage at concentrations as low as 250 nm (vs b-AP15 500 nm)." (PMID 27813535, 2016). "Shen report that in vitro selectively targeted tumor cells with BRCA1, BRCA2, or PTEN gene defects with 20–to more than 200–fold greater potency than existing PARP1/2 inhibitors." (PMID 27231574, 2016). "In the same hospital, significantly different expressions between matched tumour and healthy adjacent tissues were observed for 6 genes (APEX1, DDB1, ERCC1, NEIL1, PARP1, RPA2) after snap freezing collection." (PMID 27383461, 2016). "However loss-of-function may not always manifest at the genetic level for both genes, for example PARP1/2 do not show genetic loss in tumours." (PMID 26781748, 2016). "We assessed the DNA damage response and tumor growth inhibition in 2 NSCLC xenograft models: Calu-6 xenografts (hypoxic) and Calu-3 xenografts (well-oxygenated), following radiation and the PARP1/2 inhibitor olaparib treatment." (PMID 27020103, 2016). "Down-regulation of PARP1 due to cleavage in LNT-treated mice really occurred, demonstrating that LNT induced tumor cell apoptosis through caspase-dependent signaling pathway in vivo." (PMID 27353254, 2016). "In addition, we examined whether PARP1 inhibition has different effects among the tumor types." (PMID 26540566, 2015). "A role for PARP itself in rucaparib’s vasoactivity was investigated using tumor vessel perfusion mismatch and dorsal window chamber analyses in C57BL/6 WT and PARP-1-/- mice." (PMID 25689628, 2015). "Immunohistochemical staining indicated that the expressions of PARP1 and FOXO3A were mainly localized to the nuclei of tumor cells with weak expression in the cytoplasm, therefore, we considered only the nuclear expression of PARP1 and FOXO3A in the analysis." (PMID 26540566, 2015). "PARP1 is known to control the expressionof heat shock protein 70 (HSP70), which significantly contributes tothe survival of tumor cells and their resistance to antitumor agents." (PMID 26483957, 2015). "In tumor cells, BMN 673 (talazoparib) induced greater accumulation of PARP1 and PARP2 in the chromatin-bound fraction compared to olaparib and rucaparib." (PMID 26528434, 2015). "Deletion of PARP1 and PARP2 results in increased DNA damage sensitivity, increased genomic instability and, in case of PARP1, increased tumor formation." (PMID 24065984, 2013). "al. found that interactions with HES1 stimulates PARP1 activation and cleavage, ultimately resulting in apoptosis in B-ALL (overall a tumor suppressor role for HES1)." (PMID 23816051, 2013). "All the tumours showing the simultaneous overexpression of CAF-1/p60, PARP-1 and nestin, developed, during follow-up, recurrence and/or metastases or death." (PMID 22882088, 2012). "GSK3B-53BP1 axis controls HR-mediated DSB repair and determines synthetic lethality response of tumor cells to PARP1 inhibition independent of BRCA1 status." (PMID 41243969, 2025). "Specifically, the degradation of PARP1 promotes immune activation in dendritic cells, stimulating the STING (stimulator of interferon genes) pathway, thereby enhancing T cell-mediated anti-tumor immune responses." (PMID 40225866, 2025).
tumor (continued). "Furthermore, we discovered that ARID1A exerted a tumor-suppressive function through transcriptional suppression of c-MYC and PARP1." (PMID 41049615, 2025). "Among other enzyme classes, PARP1/14 degradation mechanisms can achieve complete clearance of DNA repair enzymes, helping resolve residual activity and drug resistance issues faced by traditional PARP inhibitors in tumor therapy." (PMID 41049269, 2025). "The observed effect of FAM111A depletion on PARP1 inhibitor-mediated cell viability suggests that tumor cells with very low levels of FAM111A, may be more sensitive to PARP1 inhibitors." (PMID 40446667, 2025). "As demonstrated in several in vitro experiments on human tumor cell cultures, within BER, PARP1/2 function as central players in SSBs and catalyze poly (ADP-ribose) (PAR) synthesis on chromatin-associated proteins, thereby recruiting downstream factors that coordinate end processing and ligation." (PMID 41440218, 2025). "In triple‐negative breast cancer, USP15 stabilizes PARP1 through deubiquitination → enhances base excision repair (BER); ER/PR/HER2 deficiency → ↑USP15–PARP1 interaction → promotes tumor growth and survival." (PMID 40904702, 2025). "In fact, PARP-1 expression is not homogeneous in tumor cells, but appears to be higher in cells with CSC characteristics." (PMID 39858519, 2025). "In addition, we reported a novel way of CYP3A5 in mediating tumor chemoresistance, which is mediated by modulating NAD+/NADH levels to impact PARP1 DNA repair activity." (PMID 39754188, 2025). "Specifically, PARP1 and PARP2 expression were higher in MSI more than MSS tumours, and in Hypermutated more than either chromosomal instability (CIN)/Epithelial or genome-stable (GS)/Mesenchymal tumours." (PMID 40573300, 2025). "Overall, higher PARP1 selectivity over PARP2, durable DNA trapping capability, improved PK and PD properties, favorable tumor‒to‒plasma distribution ratios, and potent antitumor activity show promise for enhancing the clinical efficacy of VB15010 and reducing hematological toxicity in patients." (PMID 40521389, 2025). "Moreover, PARP1 mediates the activity of the E2F1 transcription factor and affects cell cycle progression in embryonic development and tumor growth." (PMID 38481797, 2024). "Since HMGA1 and PARP1 synergistically promote DNA damage repair, we hypothesized that inhibiting HMGA1 could sensitize tumour cells to PARP1 inhibitors like olaparib." (PMID 39690136, 2024). "However, NMRGs with significant AUC values (ENPP1, ENPP2, NAMPT, SIRT1, PARP1, NMNAT1, and PNP) were differentially expressed among tumor grades." (PMID 38254798, 2024). "Considering the paired sample differential analysis, expression correlation analysis, immunological and tumour microenvironment correlation analysis, as well as the line chart results, CEMACAM3, LCK, PARP1, PDGFB, PLK1, SEMA7A and SPHK1, were considered as prognostic genes of higher value." (PMID 39656479, 2024). "We also analyzed the relationship of NHEJ pathway-related genes expression and tumor metastasis of UVM patients in a BioStudies database and found that expression of XRCC6, PRKDC and PARP1 was significantly higher in patients with metastasis than in those without metastasis." (PMID 38654216, 2024). "In glioblastomas, PARP-1 is expressed in the tumor cells, but not in normal neurons from controls or from tissue outside the tumor." (PMID 39062119, 2024). "Immunohistochemistry was performed for tumor and skin tissues according to the standard procedure using the following primary antibodies: XRCC6 (ab92450; Abcam), LIG4 (ab193353; Abcam), PARP1 (ab191217; Abcam), DNA-PK (#38168; Cell Signaling) and XRCC5 (WH0007520M2; Sigma-Aldrich)." (PMID 38654216, 2024). "Inhibition of PARP-1 could improve CRC chemotherapy beyond defects of BRCA1/2, leading to synergistic cytotoxicity in tumor cells." (PMID 39456536, 2024).
tumor (continued). "In addition, PARP1 and TNF-α29, PARP1 and IKK/NF-κB, and IKK/NF-κB and TNF-α30–32 have regulatory effects in tumours that influence tumour occurrence and development." (PMID 38388665, 2024). "In spite of the fact that disulfiram and copper (DSF/Cu) fail to suppress tumor growth, disulfiram upregulates PD-L1 and inhibits T-cell infiltration by inhibiting PARP1 activity and improving GSK3 phosphorylation at Ser9 through the PARP1 gene." (PMID 38357312, 2024). "However, increasing evidence suggests that PARP1 also plays a crucial role in mediating the complex DSB repair pathway in response to severe DNA damage induced by radiotherapy, thereby promoting tumor radioresistance." (PMID 39528473, 2024). "Our study found that in patients with GC without BRCA1 mutations, the PARP1 inhibitor OLP combined with AIL inhibiting BRCA1, and they work hand in hand to inhibit HR and BER pathways with powerful anti‐tumour effects." (PMID 38009603, 2024). "Administration of thioparib (10 mg/kg, qd) for 3 weeks significantly suppressed tumor growth compared with vehicle (P < 0.001) in the PARP1 KO MC38 model; however, no antitumor activity was observed in PARP7 KO tumor‐bearing mice." (PMID 36652375, 2023). "PARP1 and PARP2 have diverse biological functions ranging from the regulation of DNA repair, cell death, RNA transcription, protein translation, cellular bioenergetics, lipid homeostasis, tumor biology, oxidative stress, and aging." (PMID 37351597, 2023). "Although PARP-1 plays a role in detecting DNA strand breaks and regulating BER, NHEJ and chromatin remodelling, PARP-1 inhibitors are not toxic per se, but they strongly impact the sensitivity of mutant tumor cells defective in HR." (PMID 38068493, 2023). "Besides KLF4 we also detected PARP1, which was recently described to inhibit MICA expression on AML cells as part of the tumor immune evasion strategy which validates the approach." (PMID 37143070, 2023). "Mechanistically, NAMPT may modulate SIRT1 and PARP1 activity to regulate stem cell signaling pathways, thus influencing the EMT and tumor cell dedifferentiation." (PMID 38116009, 2023). "While there is a correlation between the PARP-1 trapping activity of PARPi and their toxicity in cell lines, three different PARPi exhibited similar tumor growth inhibition, regardless of their PARP-1 trapping potency." (PMID 37609662, 2023). "Plumbagin down-regulates the expression of Akt-1, PARP-1, and MMP-2 (metalloproteinase 2) and up-regulates the expression of caspase 9 and TIMP-2 (tissue inhibitor of MMP-2), ultimately inducing apoptosis in tumor cells." (PMID 37630248, 2023). "Although the decrease in invasion and metastasis after PARP-1 inhibition could easily be explained by disruption of ETS-driven transcriptional activity, the impact on tumour growth and cell survival is more surprising." (PMID 37686260, 2023). "Hematoxylin and eosin (H&E) stain, both the PDSOs and matched patients’ tumor showed atypical spindle cell proliferation in LMS, LS, and DFSP patients.Both PDSOs and patients’ tumor displayed similar expression of markers, including Ki67, CD34, PARP1, VIM, and MMP9." (PMID 37686615, 2023). "Inhibitors of PARP1/2 (PARPi) became of interest due to synthetic lethality wherein tumor cells lacking BRCA1/2 function are especially sensitive to PARPi, leading to specifically targeted tumor cell death." (PMID 37844763, 2023). "[123I]CC1 also induced increased expression of PARP1 and PARP2 in tumor cells in vitro." (PMID 37770109, 2023). "Interestingly, the tumor cells in two TNBC groups displayed different expression patterns of the critical immunotherapeutic targets, such as PD-1/L1, CTLA4, CD47, CDK4/6, PARP1/2 and DDR1/2." (PMID 36998014, 2023). "Although research has frequently explored PARP-1 regulation of DNA in tumor cells, less is known about PARP-1-mediated regulation in normal cells." (PMID 37351512, 2023).
tumor (continued). "In 2005, two studies showed that the inhibition of PARP1 activity is specifically cytotoxic in cells lacking functional forms of the tumor suppressors BRCA1 or BRCA2." (PMID 37509303, 2023). "PARP-1 and PARP-2 play a critical role in DNA repair, but they may also promote carcinogenesis and tumor progression in tissues." (PMID 36768904, 2023). "Both PARP-1 and PARP-2 are the major pathways for DNA repair in tumor cells." (PMID 37165402, 2023). "Though PARP-1 expression levels were similar between the PC-3 and IGR-CaP1 cell lines, PC-3 cells showed increased sensitivity to [77Br]Br-WC-DZ in in vitro assays in terms of cytotoxicity, clonogenic survival, and in in vivo xenograft tumor suppression." (PMID 36834491, 2023). "Although the comprehensive mechanisms of the PRMT6/PARP1/CRL4B complex remain to be fully elucidated, our study reveals that the PRMT6/PARP1/CRL4B complex transcriptionally represses the core clock gene PER3, interrupting circadian clock oscillation, thereby promoting tumor progression." (PMID 36941223, 2023). "The [77Br]Br-WC-DZ displayed high binding affinity (Kd = 0.58 ± 0.25 nM) for PARP-1 and low non-specific binding, as determined by saturation binding studies in PC-3 tumor xenografts." (PMID 36834491, 2023). "Furthermore, using CRC PDX models, we assessed the tumor suppressive effect of the combination of 5-FU and olaparib to explicate the partnership of MARVELD1 and PARP1." (PMID 36750717, 2023). "Our results provide strong rationale for the use of HR inhibitors, as well as ATRi (which are also known to indirectly suppress HR) in particle therapy to further sensitize tumor cells and also suggest the use of RAD52 and PARP1 inhibitors to further enhance efficacy." (PMID 36263011, 2022). "At first look, these agents display moderate tumor uptake compared to considerable uptake in non-target organs (e.g., high PARP1 expressing organs such as the spleen), but toxicity studies showed tolerable safety profiles at efficacious doses in mice." (PMID 35267438, 2022). "TAX promoted the expression of the pro-apoptotic molecules such as Bax, Caspase-3, Caspase-9, Cyt-C and inhibited the expression of the anti-apoptosis molecules such as Bcl-2 and PARP1, indicating that TAX efficiently induced apoptosis in tumor cells in mRNA or protein levels." (PMID 36230568, 2022). "As molecular mechanisms of 7-MG are known (PARP1/2 and TGT inhibition), a thorough investigation of its anticancer properties could be initiated in vivo, involving various transplantable tumor models and a set of existing drugs as active controls." (PMID 35873588, 2022). "From the in vitro results, olaparib could contribute to suppression of tumor invasion, and the different olaparib effects on E-cadherin in the SAS cell line would be the possible clue to the pivotal role of PARP1 activity in EMT." (PMID 35269669, 2022). "Moreover, compared to the WT tumor, Ubr5−/− tumor exhibited increased apoptosis by TUNEL staining and elevated levels of cleaved caspase-3 and cleaved PARP1 by immunohistochemistry (IHC) staining, respectively." (PMID 35551175, 2022). "This strengthens the possibility of tumour targeted PARP1 mediated nuclear uptake of [125I]PARPi-01 and a non-nuclear uptake in liver and thyroid." (PMID 36104637, 2022). "Here we show that tumor-secreted lactate downregulates p62 transcriptionally through a mechanism involving reduction of the NAD+/NADH ratio, which impairs poly(ADP-ribose)-polymerase 1 (PARP-1) activity." (PMID 35545049, 2022). "Furthermore, it was demonstrated that PARP1 works as a transcriptional coactivator for PKM2 driving the expression of glycolytic genes (GLUT and LDH) in tumor cells." (PMID 35211121, 2022).
tumor (continued). "PARP1 expression is required for the efficacy of PARP inhibitor and may drive anti-tumor activity of combination treatment with PARP inhibitor." (PMID 35419627, 2022). "Moreover, PARP1, a drug response gene of PARP inhibitors, can inhibit BRCA1/2-mediated DNA repair by homologous recombination, thereby inducing tumor cell apoptosis." (PMID 35739271, 2022). "PARP1 also interacts with EWS-FLI1, and PARP1 inhibitors inhibit tumor growth." (PMID 36194562, 2022). "Small-molecule p97-complex inhibitors, including a metabolite of the clinically used drug disulfiram (CuET), prolonged PARP1 trapping and enhanced PARP inhibitor-induced cytotoxicity in homologous recombination-defective tumour cells and patient-derived tumour organoids." (PMID 35013556, 2022). "PARP1 also regulates the transcription factor E2F1, which reduces apoptosis in tumour cells." (PMID 36078035, 2022). "In tumours with high levels of NAPRT, tumour cells may have a better supply of NAD+, which allows for the activation of NAD+-dependent enzymes, including PARP1, which are required to protect against DNA damage and oxidative stress." (PMID 36078035, 2022). "Secondly, GSCs only account for a small fraction of the total tumor cells with a significant increase in PARP1 expression as compared to the non-stem cell population." (PMID 35892832, 2022). "Furthermore, APEX2 mRNA levels positively correlated with PCNA, APEX1, XRCC1, PARP1, CHEK1, and CHEK2 across these tumor tissues." (PMID 33525741, 2021). "The CRISPR/Cas9-containing exosomes could suppress the expression of poly (ADP-ribose) polymerase-1 (PARP-1) to induce the tumor apoptosis and enhance the chemosensitivity of tumor cells to cisplatin." (PMID 34683943, 2021). "As a tumor suppressor gene,upregulation of TRAF3IP2-AS1 markedly inhibited PARP1 expression by binding to its mRNA directly to stimulate m6A methylation which led to mRNA decay of PARP1 and enhanced the expression of PTEN through absorbing miR-200a-3p, miR-153-3p and miR-141-3p." (PMID 33741027, 2021). "Expression of PARP1 and SLFN11 was present in the majority of UV AS tumor samples." (PMID 34085099, 2021). "PARP1 can inhibit the expression of PD-L1 on the surface of TNBC cells by interacting with the nucleic acid-binding domain of nucleophosmin, thus playing a key role in the tumor-related immune escape of TNBC." (PMID 34408776, 2021). "This process of BHRF1+/SNHG8 high/miR-512-5p low/TRIM28high in EBVaGC directly enhances the activation of a set of tumor-promoting factors, such as proliferation-related genes (BCL-2, CCND1, PCNA, PARP1) and metastasis-related genes (Snail, VIM, CDH1, and CDH2)." (PMID 34722282, 2021). "This PARP1-mediated progression is supported by evidence of higher PARP1 expression in tumours of patients with liver metastases than of their non-metastatic counterparts." (PMID 34440228, 2021). "Additionally, the activity of DNA repair enzymes such as PARP1 are inhibited by restricted NAD+ availability, which halts tumour progression." (PMID 34680055, 2021). "These pathway correlations support the hypothesis that NAMPT modulates SIRT1 and PARP1 to control the cellular functions that promote proliferation and stemness pathways, thus regulating the EMT and tumor dedifferentiation." (PMID 33384409, 2021). "Unlike the primary oral tumor cells, recurrent tumor cells gained the capability of inducing PARP1 expression upon cisplatin or 5-fluorouracil treatment." (PMID 35071239, 2021).